OTOF (otoferlin)
Diseases named in the same sentence as OTOF in open-access papers (continued):
Sharing a sentence is not in itself a finding about the gene and the disease.
deafness (continued). "Furthermore, we observed that the presence of additional mutations in other deafness-associated genes, such as SLC26A4 and OTOF, was associated with more severe auditory impairment." (PMID 40943139, 2025). "Indeed, after demonstrating OTOF’s involvement in DFNB9 deafness studies have demonstrated that delivering OTOF cDNA via AAVs into hair cells is sufficient to restore the hearing of OTOF −/− mice." (PMID 41227304, 2025). "As an example of target genes, we selected the two well-known deafness genes OTOF and TECTA." (PMID 38474154, 2024). "This is the first report of a KO OTOF model in large animals, which could be useful to better understand of deafness in humans as well as to test different therapies to treat this genetic disorder." (PMID 32265471, 2020). "These mutations in CDH23 and OTOF were only found in respectively patients 1–2 and 4 and not in the other analyzed deafness samples (e.g. we often did find the same SNP’s in different patients)." (PMID 22607986, 2012). "For example, we recently found that four prevalent OTOF variants account for about 70% of Korean prelingual auditory neuropathy spectrum disorder (ANSD) with the anatomically intact cochlear nerve, making it unnecessary to go through other deafness genes irrelevant to such a phenotype." (PMID 32899707, 2020). "The known deafness genes with variants detected in this study were GJB2 (MIM 121011; 21.2%), TMPRSS3 (MIM 605551; 6.1%), MYO15A (MIM 602666; 6.1%), TMC1 (MIM 606706; 3%), ADGRV1 (MIM 602851; 3%), PTPRQ (MIM 603317; 3%), SLC26A4 (MIM 605646; 3%), and OTOF (MIM 603681; 3%)." (PMID 31379920, 2019). "We analyzed the influence of the four selected reference genes on the expression profile of OTOF and TECTA, two deafness-related genes." (PMID 38474154, 2024). "Despite the genetic heterogeneity, some genes showed greater contribution to cases of autosomal recessive deafness in our study: GJB2, CDH23 (10.34%), MYO15A (7%), OTOF (7%), and USH2A (7%)." (PMID 39498320, 2024). "Among the 98 deafness-related genes detected in this study, SLC26A4 (62.7%, 32/51), MYO15A (63.6%, 14/22), OTOF (40.0%, 4/10) and PTPRQ (75.0%, 3/4) contained intronic variants." (PMID 36597107, 2023). "The most prevalent deafness genes identified in our cohort include SLC26A4 (22%), GJB2 (13%), MYO15A (6%), and OTOF (6%); whereas those identified in the American patients were GJB2 (36%), SLC26A4 (13%), MYO7A (8%), and MYO15A (8%)." (PMID 36009393, 2022). "Furthermore, because of the extreme heterogeneities of causative genes, studies of molecular etiology have focused mainly upon deafness genes, such as, GJB2, SLC26A4, or OTOF, which make larger contributions to deafness in local populations." (PMID 25373420, 2014). "Mutations in OTOF gene, encoding otoferlin, cause DFNB9 deafness and non-syndromic auditory neuropathy (AN)." (PMID 20504331, 2010).
hearing loss (48 papers, 2010 to 2026). "Background/Objectives: The OTOF gene is reported to be the causative gene for non-syndromic recessive sensorineural hearing loss and auditory neuropathy spectrum disorder." (PMID 40004445, 2025). "While pathogenic OTOF variants are a well-established major cause of this disorder, the prevalence of specific variants and the overall prevalence of OTOF-associated hearing loss exhibit significant inter-population variability." (PMID 40346465, 2025). "For instance, a splicing variant of OTOF (NM_194248, c.3289-1G > T) was found to segregate with a profound hearing impairment phenotype in a Pakistani family." (PMID 39230647, 2025). "For example, let us re-consider the current movement around the OTOF gene as a cure for congenital hearing loss." (PMID 40003934, 2025). "Five pediatric patients (two girls and three boys) with bilateral congenital hearing loss caused by biallelic OTOF mutations were enrolled from 14 July 2023 to 15 November 2023." (PMID 38839897, 2024). "A major form of congenital hearing loss is caused by genetic mutations in OTOF, coding for otoferlin, which is important for synaptic vesicle exocytosis in inner hair cells of the cochlea and transmission of auditory signals to the brain." (PMID 38785523, 2024). "The OTOF gene, responsible for producing the otoferlin protein, is a prominent factor in non-syndromic recessive sensorineural hearing loss." (PMID 38525683, 2024). "Attenuation of otoacoustic emissions over time has been reported for many patients with hearing impairment harboring mutations in the OTOF gene." (PMID 37677959, 2024). "The most promising results about a genetic therapy for autosomal recessive congenital hearing loss are those associated with hearing impairments caused by OTOF mutations." (PMID 38525683, 2024). "As bilateral cochlear implantation is the standard of care for children with severe to profound hearing loss, it is likely that profoundly-deaf children harboring mutations in the OTOF gene received the bilateral cochlear implant by 1 to 2 years of age." (PMID 37677959, 2024). "Sequence variations in OTOF, which encodes the calcium-binding protein otoferlin, are responsible for 1–8% of congenital, nonsyndromic hearing loss and are the leading cause of auditory neuropathy spectrum disorders." (PMID 37679651, 2023). "Our findings are consistent with previously reported pathogenic variants in the MYO15A and OTOF genes in Middle Eastern individuals and suggest their implication in hearing loss." (PMID 37189200, 2023). "Auditory neuropathy spectrum disorder (ANSD) associated with mutations of the OTOF gene is one of the common types of sensorineural hearing loss of a hereditary nature." (PMID 38139069, 2023). "Considering that pre-clinical research for the use of gene-based therapy to treat hearing loss only began about 15 years ago, there has been substantial progress made with three groups advancing towards clinical trials for the OTOF gene." (PMID 37325593, 2023). "Another study reported a stop-gain variant Q829X in OTOF, which is associated with auditory neuropathy, in patients with prelingual non-syndromic hearing loss." (PMID 35209959, 2022). "Mutations in the OTOF gene are a common cause of hereditary hearing loss and the main cause of auditory neuropathy spectrum disorder (ANSD)." (PMID 34536124, 2022). "Mutations in the gene OTOF encoding for the protein otoferlin cause hearing impairment with autosomal recessive inheritance, DFNB9." (PMID 34335185, 2021). "The combination OAE recordings and ABR or pure tone audiometry are, in principle, sufficient to diagnose hearing impairment due to OTOF mutations." (PMID 33256196, 2020). "Earlier studies confirmed that Rab8b is an interacting partner of Otoferlin, which is a protein associated to hearing loss." (PMID 33101391, 2020). "In this study, we conducted a genetic analysis of the OTOF gene in 2,265 Japanese hearing loss patients by MPS." (PMID 31095577, 2019).
hearing loss (continued). "The mutation analysis of 68 genes, including the OTOF gene, reported to cause non-syndromic hearing loss was performed using MPS." (PMID 31095577, 2019). "It is assumed that the frequency of hearing loss associated with OTOF mutations is about 1.72% of autosomal recessive or sporadic SNHL cases." (PMID 31095577, 2019). "Hearing level information was available for 32 of 39 patients with biallelic OTOF mutations; 24 of them (75.0%) showed profound hearing loss, 7 (21.9%) showed severe hearing loss and 1 (3.1%) showed mild hearing loss." (PMID 31095577, 2019). "It was previously reported that OTOF mutations accounted for 1.4–8.3% of non-syndromic hearing loss patients: 2.3% (13/557) in Pakistani, 3.2% (23/708) in Spanish, 8.3% (1/12) in Turkish, 2.6% (1/38) in Iranian and 1.4% (1/73) in Chinese populations." (PMID 31095577, 2019). "Hearing level information was available for 32 of the 39 patients with biallelic OTOF mutations; 24 of them (75.0%) had profound hearing loss, 7 (21.9%) had severe hearing loss and 1 (3.1%) had mild hearing loss." (PMID 31095577, 2019). "To date, more than 160 mutations in OTOF have been reported, and most of the patients with OTOF mutations have stable, prelingual and severe to profound hearing loss." (PMID 31095577, 2019). "The hearing levels in patients with biallelic OTOF mutations in this study were mostly severe to profound: 75.0% (24/32) had profound hearing loss, and 21.9% (7/32) had severe hearing loss." (PMID 31095577, 2019). "Our study included 1,123 patients with severe-profound hearing loss, and 30 (2.67%) of these patients had biallelic OTOF mutations, a rate which is comparable with that of our previous report." (PMID 31095577, 2019). "The present study identified 11 possibly pathogenic OTOF variants in Japanese patients with nonsyndromic hearing loss, and 6 of them were novel mutations (p.D450E, p.W717X, p.S1368X, p.R1583H, p.V1778I, and p.E1803A)." (PMID 24053799, 2013). "The aim of this study was to determine what portion of nonsyndromic hearing loss is caused by mutations of OTOF, the major responsible gene for nonsyndromic ANSD." (PMID 24053799, 2013). "OTOF gene mutations have been inferred to be responsible for 2%–3% non-syndromic hearing losses (NSHL) in some ethnic groups, and most of these patients meet the diagnostic criteria for ANSD." (PMID 21935370, 2011). "The studies of OTOF, and other ferlin family members, including fer-1, have contributed to the understanding of ferlin protein function and the development of gene therapies to cure hearing loss in individuals with OTOF mutations." (PMID 39982357, 2025). "OTOF variants have been identified as the cause of hearing impairment in approximately 5% of Turkish patients, 3% of Pakistani patients, 2.4% of European-American patients, 1.9% of French patients, and 1.7% of Japanese patients who were not pre-selected for ANSD." (PMID 40346465, 2025). "Further research had found that downregulation of OTOF protein levels can lead to hearing loss." (PMID 40718794, 2025). "In this study, we retrospectively analyzed the changes of distortion product otoacoustic emissions (DPOAEs) in a group of 16 patients with hearing impairment due to mutations in the OTOF gene in the light of the tympanometry measures collected on the same OAE recording session." (PMID 37677959, 2024). "Furthermore, we found three active clinical trials testing AAV gene therapy and recruiting patients diagnosed with hearing loss caused by biallelic OTOF gene mutations." (PMID 38525683, 2024). "OTOF is the most common gene in our infant subgroup, previous studies showed that biallelic OTOF variants cause congenital or early onset (n = 114) hearing impairment mainly, and only few variants have been identified with progressive hearing loss (n = 3)." (PMID 38456936, 2024). "Generally, biallelic OTOF variants cause congenital or early onset (n = 114) hearing impairment." (PMID 33256196, 2020).
hearing loss (continued). "OTOF mutations were found in 2.4% of individuals with hearing loss." (PMID 32290039, 2020). "Although we previously reported the prevalence of hearing loss with OTOF mutations on the basis of Sanger sequencing, it is both time-consuming and costly to analyze a large number of patients by this method as the OTOF gene has a large number of exons." (PMID 31095577, 2019). "Moreover, some missense mutations in OTOF have been reported in patients showing a temperature-sensitive phenotype, while few have been associated with progressive hearing loss." (PMID 33908410, 2021). "Among these elements, we identified six potential variants in cis-regulatory elements associated with hearing loss genes, CDH23, OTOF, MYO6, COL4A4 and WHRN." (PMID 40164689, 2025). "Other studies also indicated that, apart from GJB2, pathogenic variants in SLC26A4, MYO15A, OTOF, and CDH23 are a frequent cause of hearing loss in European populations (Hilgert, Smith, Van Camp, 2009)." (PMID 39498320, 2024). "The authors focused on DFNB9 (MIM601071), which accounts for 2–8% of cases of prelingual hearing impairment and is caused by biallelic mutations of the OTOF gene, encoding otoferlin." (PMID 36769694, 2023). "OTOF is reported to be the causative gene of DFNB9 and one of the common causes of non-syndromic recessive sensorineural hearing loss." (PMID 34536124, 2022). "In this study, only 1 patient (3.1%) had mild hearing loss; however, both mutations carried by the patient were variants of uncertain significance (p.D217G and p.A1802V), and it is unclear whether the true etiology of the hearing loss in this patient is due to mutations in the OTOF gene." (PMID 31095577, 2019). "Future molecular testing for etiology of hearing loss will need to include mutations in other genes, such as OTOF, encoding otoferlin, in which mutations are commonly found in children with ANSD." (PMID 23555729, 2013). "Mutations in the MYO15A, OTOF, TMC1 and other genes have emerged as being among the more prevalent nonsyndromic hearing loss mutations, worldwide." (PMID 20668687, 2010). "Pre-clinical research on ATOH1 and OTOF are always conducted on animal models rather than model animals therefore the research findings will never reliably translate to clinical forms of hearing loss." (PMID 40003934, 2025). "Although the significance of the two otoferlin isoforms for human hearing impairments remains to be shown, we suggest that people with nonsense mutations located in exons 1–6 may suffer from HHL." (PMID 37248244, 2023). "OTOF sequence variants can result in deficient or non-functional otoferlin protein, thus disrupting synaptic transmission and causing otoferlin-related hearing loss." (PMID 37679651, 2023). "OtofIle515Thr/Ile515Thr mice exhibited moderate hearing impairment with lower otoferlin levels and enlarged synaptic vesicles in the IHCs, suggesting that mutations around the area in the C2C domain may cause a milder phenotype." (PMID 34536124, 2022). "Presumably due to the residual otoferlin function, OAEs remained preserved in these intermediate forms of hearing impairment; thus, affected individuals may be candidates for gene therapies even in adulthood." (PMID 33256196, 2020). "Mutations of OTOF are responsible for a form of nonsyndromic autosomal recessive sensorineural deafness, DFNB9, defined by a severe to profound congenital or prelingual hearing impairment but preserve vestibular functions." (PMID 32290039, 2020). "Mutations in OTOF and PJVK genes cause DFNB9 and DFNB59 types of hearing loss, respectively." (PMID 21935370, 2011). "Although mutations in the OTOF gene are not major contributors to hearing loss in Iran—the second largest country in the Middle East, they are prevalent in other neighbouring countries, namely Turkey and Pakistan, as well as the Gulf Cooperation Council (GCC) countries." (PMID 37189200, 2023).
hearing loss (continued). "Notably, no other genes apart from OTOF have been associated with temperature-sensitive forms of hearing loss and all cases presenting a similar phenotype in the literature have disclosed pathogenic OTOF variants, regardless of population background." (PMID 33256196, 2020). "The OTOF gene was first cloned and identified in a Lebanese family with DFNB9 non-syndromic hearing loss, which was not originally diagnosed as ANSD." (PMID 21935370, 2011).
auditory neuropathy (44 papers, 2010 to 2026). A hearing disorder characterized by impaired transmission of signals through the auditory nerve, resulting in mild to severe hearing loss and poor speech perception. "Variants in the OTOF gene are associated with a special auditory condition called auditory neuropathy spectrum disorder (ANSD)." (PMID 40003934, 2025). "Special concern has been raised for targeting the OTOF gene, which causes auditory neuropathy spectrum disorder (ANSD), as well as DFNB9, an ARNSHL." (PMID 40858759, 2025). "Auditory neuropathy is associated with the p.Pro50Arg, p.Ile515Thr, p.Gly541Ser, p.Glu551fs, p.Leu1011Pro, and p.Arg1939Gln mutations in OTOF." (PMID 39982357, 2025). "This study aims to revisit the genetic landscape of OTOF variants in a Taiwanese non-syndromic auditory neuropathy spectrum disorder (ANSD) cohort using a combination of sequencing technologies, predictive tools, and experimental validations." (PMID 40346465, 2025). "Based on mouse and cynomolgus macaque data, we next determined the efficacy and safety of AAV‐OTOF in two patients of 5 and 8 years of age with auditory neuropathy due to OTOF mutations." (PMID 38189623, 2024). "CI seems beneficial in cases of OTOF mutation and Brown–Vialetto–Van Laere syndrome-related auditory neuropathies (OMIM#211530), whereas patients will benefit less from a CI in cases of mutations affecting the auditory ganglion cells and auditory nerve." (PMID 36980899, 2023). "Even though several genes have been associated with auditory neuropathy, only a few OTOF variants have been associated with clinical pictures compatible with TS-ANSD." (PMID 36837553, 2023). "Mutations in OTOF are an important cause of auditory neuropathy spectrum disorder (ANSD), a hearing disorder characterized by a functional cochlea but a non-functional auditory nerve." (PMID 32765579, 2020). "The discovery of c.2688del and c.2675A>G mutations expands the spectrum of mutations found in the OTOF gene and provides a new reference point for the genetic diagnosis of auditory neuropathy." (PMID 33426078, 2020). "A detection of OTOF mutations can help in accurately localizing the site of lesion and informing therapy-related clinical decision making in patients with auditory neuropathy." (PMID 32508568, 2020). "Recessive OTOF mutations were the predominant genetic cause among patients with non-syndromic auditory neuropathy in this study." (PMID 32555439, 2020). "The site of lesion in patients with auditory neuropathy caused by biallelic OTOF mutations (OTOF-related auditory neuropathy) is presumed to be presynaptic, leaving auditory nerve function intact." (PMID 32508568, 2020). "As exemplified by a study that included Japanese patients with auditory neuropathy/synaptopathy, biallelic OTOF variants were uncovered in 56% of cases that included the identification of a founder variant (p.Arg1939Gln)." (PMID 33256196, 2020). "In our previous study, we confirmed that OTOF is the most common gene-causing congenital auditory neuropathy." (PMID 32684920, 2020). "Mutations in the OTOF gene were the first identified and the most common cause of congenital auditory neuropathy." (PMID 32508568, 2020). "Late-onset progressive auditory neuropathy has been reported in patients with OTOF or OPA1 mutations, this is consistent with our observation." (PMID 32555439, 2020). "Although all studies were in coherence with that the auditory neuropathy caused by OTOF mutations tend to have good CI outcomes, individual variations still exist among cases." (PMID 32508568, 2020). "Mutations in the OTOF gene (named as homology to Ferlin (Fer-1)) encoding otoferlin at DFNB9 results in ARNSHL which is sometimes associated with auditory neuropathy." (PMID 31700827, 2019). "Variants in OTOF have been reported as the main cause of nonsyndromic recessive auditory neuropathy spectrum disorder." (PMID 31250571, 2019).